CHI3L1 (chitinase 3 like 1)
Diseases named in the same sentence as CHI3L1 in open-access papers (continued):
Sharing a sentence is not in itself a finding about the gene and the disease.
tumor (continued). "In these five cases staining showed that CHI3L1 was more highly expressed in the cytoplasm of tumour cells adjacent to the necrotic regions." (PMID 18781180, 2008). "Histopathological review revealed that in five cases, where areas of necrosis were visible, CHI3L1 protein expression was restricted to the cytoplasm of viable tumour cells adjacent to the areas of necrosis." (PMID 18781180, 2008). "Mechanistically, elevated CHI3L1 expression in the mammary epithelium enhanced neutrophil recruitment, which subsequently degraded the extracellular matrix and increased the number of circulating tumor cells." (PMID 41632530, 2026). "This activation indirectly enhances CHI3L1 expression, contributing to tumor progression." (PMID 40260255, 2025). "CHI3L1, a glycoprotein, has multiple biological functions in the tumor microenvironment." (PMID 40260255, 2025). "CHI3L1 (non‐enzymatic chitinase‐3 like‐protein‐1) is a kind of the glycoside hydrolase family 18, which is synthesized and secreted by various cell types, including immune‐related cells, fibroblast‐like cells, smooth muscle cells, and tumor cells." (PMID 40084401, 2025). "Targeted intervention with CHI3L1 may inhibit the proliferation and invasion of tumor cells, thereby improving patient prognosis." (PMID 40260255, 2025). "Across all datasets, CHI3L1 was significantly upregulated in the tumor group (P < 0.05)." (PMID 40260255, 2025). "CHI3L1 can directly stimulate tumor cells to produce proinflammatory cytokines (IL-6, IL-8, and transforming growth factor-β) and activate the transforming growth factor-β signaling pathway through binding to its receptor, resulting in proinflammatory cytokine production and immune cell recruitment." (PMID 40260255, 2025). "From a therapeutic standpoint, CHI3L1 inhibition may suppress tumor growth, and therapeutic strategies, including anti-CHI3L1 monoclonal antibodies and bispecific antibodies targeting CHI3L1/PD-1, are currently under development." (PMID 40643503, 2025). "Given the potential role of CHI3L1 in T cell-based immunotherapies in various tumor types, it is speculated that targeting CHI3L1 may promote anti-tumor immunity in HCC." (PMID 40821115, 2025). "An investigation of mAY in a mouse xenograft model of glioblastoma showed that neutralization of CHI3L1 significantly inhibited tumor growth and metastasis formation in some animals, however, mAY failed to provide full protection in all treated mice." (PMID 40313579, 2025). "Targeting Chi3l1 with therapeutic antibodies is a promising strategy to reduce tumor burden in GBM." (PMID 40565099, 2025). "Additionally, by promoting the polarization of M2-type macrophages and establishing an immunosuppressive milieu, CHI3L1 supports sustained tumor growth." (PMID 40643503, 2025). "However, once CHI3L1 is abundantly secreted into the circulation, it exerts a diametrically opposite, tumor-promoting effect in the liver." (PMID 41568005, 2025). "Moreover, CHI3L1 promotes tumor invasion by upregulating the expression of matrix metalloproteinases (MMPs), enzymes that degrade the extracellular matrix, enabling tumor cells to invade surrounding tissues." (PMID 39827337, 2025). "It was found that CHI3L1 could regulate the expression of immune checkpoint molecules such as PD-L1, PD-L2, and PD-1 to promote tumor progression." (PMID 40166469, 2025). "Furthermore, CHI3L1 contributes to an immunosuppressive tumor microenvironment by promoting M2-type macrophage polarization, suppressing T cell activity, and increasing levels of IL-10 and VEGF (vascular endothelial growth factor)." (PMID 40643503, 2025). "However, after repeated weekly injections of the carcinogen Azoxymethane (AOM), CHI3L1-expressing CECs in MOLF mice show accelerated tumor growth and dysplastic changes compared to those in B6 WT mice." (PMID 40643503, 2025).
tumor (continued). "Interestingly, CHI3L1 can be released into the tumor microenvironment (TME) and interacts with CD44 expressed on tumor-associated macrophages to activate the AKT pathway, thus contributing to M2 macrophage polarization." (PMID 39827337, 2025). "These cells contribute to CHI3L1 secretion and are actively involved in critical biological processes, including inflammatory responses, apoptosis, and signal transduction, all of which can profoundly influence tumor progression and prognosis." (PMID 40260255, 2025). "Whether promoting inflammatory progression to induce tumorigenesis or maintaining the inflammatory microenvironment for tumor growth, CHI3L1 plays a crucial role in multiple stages of progressive tumorigenesis." (PMID 39068486, 2024). "Compared to anti-CHI3L1, chitin enhanced primary tumor growth reduction and anti-tumorigenicity." (PMID 38605414, 2024). "Finally, we found that the CHI3L1-inhibiting Compound K284-6111 completely reduced atopy skin inflammation." (PMID 38177294, 2024). "By contrast, CHI3L1 + macrophages mainly localize close to the tumor nest." (PMID 39702278, 2024). "CHI3L1 has been identified as a potent modulator of immune responses, particularly through its stimulation of macrophage and neutrophil activity, as well as its influence on immune checkpoints, thereby establishing a conducive environment for tumor growth." (PMID 38667293, 2024). "The YKL40 protein, also known as acidic mammalian chitinase-related protein (AMCase), is a type of cytokine that is encoded by CHI3L1 and is commonly found in various cells and tissues, including immune cells, liver, brain, and tumor tissues." (PMID 38543093, 2024). "Together, these data identify a functional and upstream role of CHI3L1 in governing tumor cell connectivity, CHI3L1 RNA and protein expression as an alternative way to determine overall tumor (cell) connectivity in GB, and finally a therapeutic target for tumor network-disrupting strategies." (PMID 38320988, 2024). "In vitro studies have demonstrated that CHI3L1(YKL40) inhibition may have an influence on angiogenesis, migration, and immune response in various tumor cells." (PMID 38543093, 2024). "CHI3L1 may promote tumor growth and migration by interacting with TGF-β1 and TGFR, thereby activating the SMAD2/SMAD3 signaling pathway." (PMID 38177294, 2024). "Therefore, 4T1 tumor-bearing mice were treated with either chitin (every 3 d), anti-CHI3L1 or IgG control antibodies (weekly) for 2 w until 5 w p.i., and tumor progression was monitored through tumor volume measurements." (PMID 38605414, 2024). "For single CLP blockade, tumor-bearing mice were treated with anti-CHI3L1 antibodies." (PMID 38605414, 2024). "Moreover, the ability of CHI3L1 to reshape the extracellular matrix (ECM) prevents tumor cells from programmed cell death (PCD)." (PMID 39000203, 2024). "In addition, it has been reported that elevated CHI3L1 accelerates HCC tumor progression by promoting ROS synthesis and inducing lipid peroxide (LPO) accumulation." (PMID 39513118, 2024). "CHI3L1 blocks T-cell infiltration by promoting neutrophil recruitment and neutrophil extracellular trap formation, and CHI3L1 targeting promotes antitumor immunity in various tumor types." (PMID 38962736, 2024). "Besides providing suppressive modulation of the host immune system, CHI3L1 has a direct impact on tumor cells by activating pathways involved in cellular proliferation, migration, stemness and survival." (PMID 38605414, 2024). "CHI3L1 is closely related to cell proliferation, apoptosis, cell differentiation, and cell invasion and is involved in embryonic development, inflammation, tissue remodeling, angiogenesis, and tumor metastasis; however, studies targeting serum CHI3L1 levels are limited." (PMID 38962736, 2024). "Similarly, it was confirmed that ER stress-mediated apoptotic marker protein levels were increased in tumor tissue and lung metastatic tissues of CHI3L1 KO mice." (PMID 37215572, 2023).
tumor (continued). "We also found that CHI3L1 is involved in various malignant tumor-associated signaling pathways, among which epithelial-mesenchymal transition, PI3K/AKT, RAS/MAPK, and TSC-mTOR were associated with tumor migration and invasion." (PMID 37480002, 2023). "The expression of the cytokine Chi3l1 was reduced in Stat3-/-tumours." (PMID 38203218, 2023). "A meta-analysis on CHI3L1 included 234 EC patients and 300 normal individuals, showing that 74% of EC patients had elevated CHI3L1 levels, indicating that CHI3L1 is indeed a valuable tumor marker for EC." (PMID 38003338, 2023). "In addition, in the xenograft model, ER chaperone protein levels were significantly increased in tumor tissues from CHI3L1 KO mice." (PMID 37215572, 2023). "However, the influence of CHI3L1 expression on the immunological properties of the CRC tumor microenvironment requires further investigation." (PMID 37185706, 2023). "In addition, the number of LC3 and LAMP-1 co-localized cells also decreased in CHI3L1-KO tumor tissues." (PMID 37340009, 2023). "Furthermore, the depletion of CHI3L1 significantly increased SOD1 expression in in vivo tumor and lung tissues." (PMID 37215572, 2023). "CHI3L1 is a member of glycoside hydrolase family 18 and is synthesized and secreted by many cells, including macrophages, neutrophils, synoviocytes, smooth muscle cells, and tumor cells." (PMID 36331721, 2023). "CHI3L1 participates in cancer progression through different pathways, such as enhancing the production of proinflammatory/pro-tumor angiogenic factors to aid tumor spread or regulating signaling pathways in tumor progression." (PMID 38003338, 2023). "The tumor infiltrating Rab37+CHI3L1+ cells were highly enriched with CD163+ M2 TAMs in the tumor sections from patients with advanced tumor stages, whereas early staged tumors displayed a low abundance of infiltrating Rab37+CHI3L1+CD163+ M2 TAMs and scattered intratumoral CHI3L1." (PMID 34987649, 2022). "M2 macrophages promote tumor metastasis by secreting chitinase 3-like protein 1 (CHI3L1) protein." (PMID 35967399, 2022). "Studies from our laboratory have demonstrated that induced expression of CHI3L1 plays a critical role in the generation of a metastasis permissive tumor microenvironment and the inhibition of CHI3L1 via RIG-like helicase (RLH) innate immune activation can also inhibit metastatic spread in the lung." (PMID 36618349, 2022). "We examined whether STAT6 inhibitor AS1517499 and anti‐Chi3L1 antibody combination treatment showed additive effects on tumor migration by STAT6‐dependent M2 polarization." (PMID 34861103, 2022). "Finally, it was also shown that a CHI3L1-neutralizing antibody synergized with trastuzumab to generate robust anti-tumor effects." (PMID 36291900, 2022). "In summary, our work suggests that the molecular subtype of epithelial tumour cells in TETs determine their tumour immune microenvironment, thus GNB3 and CHI3L1 might predict the immunological behavior and hence prognosis of these tumours." (PMID 36115836, 2022). "Increased serum CHI3L1 levels have been found to be involved in tumor development and progression." (PMID 35646113, 2022). "Furthermore, the tumor occupied 1.08 ± 0.36 of the tissue weight in vehicle‐treated mice, which significantly decreased to 0.56 ± 0.30 with anti‐Chi3L1 antibody." (PMID 34861103, 2022). "In addition, synergistic cytotoxic T cell (CTL)-induced tumor cell death and the induction of the tumor suppressor PTEN were seen in a T cell-tumor co-culture treated with bispecific antibodies that target CHI3L1 and CTLA-4." (PMID 36618349, 2022). "As a mechanism that mediates immunosuppressive responses in tumor or tumor microenvironment, we hypothesis that CHI3L1 plays a critical role in these immunosuppressive events mediated by immune checkpoint molecules." (PMID 36618349, 2022). "The overexpression of CHI3L1 in the tumor cells impaired the efficacy of ADCC in mice models." (PMID 36291900, 2022).
tumor (continued). "However, CD206 and ARG1 were dramatically reduced by the anti‐Chi3L1 antibody in lung metastatic tumor tissues." (PMID 34861103, 2022). "Additionally, the ELISA data showed a positive correlation of plasma CHI3L1 level with tumor volume in treated mice." (PMID 34987649, 2022). "The CHI3L1 (chitinase-3-like protein 1) immunohistochemistry (IHC) expression of baseline tumour samples could predict the therapeutic response (AUC=0.732), OS (P=0.017) and PFS (P=0.001)." (PMID 36581917, 2022). "Consequently, the tumors developed from the cells with CHI3L1 knockdown grew slower, and the tumor sizes were also smaller than the control group." (PMID 36276655, 2022). "Therefore, we performed tumor IHC with Rab37 and ELISA of plasma CHI3L1 from 103 PDAC patients whose tumor specimen and plasma samples were both available." (PMID 34987649, 2022). "However, in anti‐Chi3L1 antibody‐ or Avastin‐treated tumor tissues, the number of mitotic cells was lower than in vehicle‐treated tumor tissues, and the number of dead cells was higher." (PMID 34861103, 2022). "GBM is the type of tumor with the highest expression of CHI3L1 compared to other tumor types." (PMID 36276655, 2022). "Since CHI3L1 has been reported to regulate functions of different immune cells, which are important components of tumor microenvironment, we further assessed whether CHI3L1 expression level correlated with the infiltration of different immune cells." (PMID 34612767, 2021). "Due to the proangiogenic role of CHI3L1 in various tumor cells, we determined to explore whether CHI3L1 also mediates neovascularization in atherosclerotic plaques." (PMID 34349665, 2021). "However, to obtain a comprehensive picture of the CHI3L1-related alterations of the tumor microenvironment further research is required." (PMID 33920100, 2021). "Activation of IL-13Rα2 by CHI3L1 triggers the activation of the mitogen-activated protein kinase signaling pathway, upregulating matrix metalloproteinase genes expression and promoting tumor metasta." (PMID 34722557, 2021). "Molecular targeting of CHI3L1 or regulating its activity within the tumor microenvironment may therefore represent a novel strategy to support current immunotherapies." (PMID 33920100, 2021). "ROC curve demonstrated that the variable CHI3L1 expression level could predict the tumor samples with certain accuracy (AUC = 0.815, CI = 0.625–1.000)." (PMID 34612767, 2021). "CHI3L1 may affect tumor development and metastasis by promoting angiogenesis, cell migration and by tuning the tumor microenvironment and tumor inflammation." (PMID 33920100, 2021). "Our data suggest that CHI3L1 may tune the composition of the tumor microenvironment by the preferential release of specific cytokines or growth factors." (PMID 33920100, 2021). "There was a significant difference in tumor growth between con shRNA and Chi3L1 shRNA mice." (PMID 32127023, 2020). "In the present study, we investigated whether G721-0282, a candidate ligand of Chi3L1 regulates in vitro effects on proliferation, apoptosis, migration, invasion, and colony formation in OS cells, and in vivo anti-tumor effects in a xenograft mouse model." (PMID 31929760, 2020). "CHI3L1 is overexpressed in a multitude of human cancers and animal tumor models." (PMID 32929074, 2020). "CHI3L1 is synthesized and secreted by a multitude of cells including macrophages, neutrophils, synoviocytes, chondrocytes, fibroblast-like cells, smooth muscle cells, and tumor cells." (PMID 32929074, 2020). "We also present that CHI3L1 related signal was mediated by CHI3L1-IL13Rα2 binding in tumor cells." (PMID 31561550, 2019).
tumor (continued). "CHI3L1 and LCN2 are strongly produced by tumor cells and TAM, and besides their immunomodulatory function both biomarker proteins have been linked to several tumor-promoting processes such as EMT, (lymph)angiogenesis and matrix remodeling." (PMID 30111338, 2018). "A CHI3L1-neutralizing antibody restrained tumor growth, angiogenesis, and progression." (PMID 30165890, 2018). "Consistent with the RNA-sequencing and RT-PCR results, Chi3l1 KO mice had increased mRNA for anti-tumor immunity molecules including CTSE, TRAL, IFNγ, T-bet, Perforin, and Granzyme B, while the expression of Th1-inhibitory molecules such as Twist1 and SOCS1 was significantly reduced." (PMID 29403003, 2018). "Together, these findings suggest that CHI3L1 could be a therapeutic target to inhibit tumor progression and enhance anti-tumor immunity." (PMID 30165890, 2018). "Thus, our findings identify, for the first time, that circulating immune cells from advanced metastatic PCa patients secrete higher levels of CHI3L1, leading to increased invasion of tumor cells." (PMID 30094958, 2018). "The increase of effector functional molecules in Chi3l1-deficient T cells prompted us to investigate whether Chi3l1-deficient Th1 and CTL contributed to anti-tumor immunity." (PMID 29403003, 2018). "In this context, the upregulated miRNAs in shrimp in response to WSSV challenge might be good candidates for discovering anti-tumor miRNAs by targeting CHI3L1 gene." (PMID 30258444, 2018). "Our results indicated that GZZSZTW significantly increased the expression levels of multiple genes involved in promoting cell proliferation, most of which are highly expressed in tumor cells, such as Tnfaip2, Chi3l1, Tnf, Pfkfb3, Sox8, Jag1, Mafb, Pla2g7, Hnrnpa1, and E2f3." (PMID 30275866, 2018). "Thus, we show that circulating monocytes from metastatic PCa patients exert a tumor‐promoting role via the secretion of CHI3L1, and CHI3L1 demands further exploration as a possible therapeutic target in advanced PCa." (PMID 30094958, 2018). "As reported, the CHI3L1 protein can be produced by various cell types, including differentiated macrophages, neutrophils, synovial cells, osteoblasts, chondrocytes, vascular smooth muscle cells, and tumor cells." (PMID 30258444, 2018). "Chi3l1 KO CD8 T cells showed more potent tumor-killing activity than WT CD8 T cells." (PMID 29403003, 2018). "Moreover, the conjunction therapy with the CHI3L1-neutralizing antibody and ionizing irradiation synergistically inhibited tumor vascularization and progression." (PMID 30165890, 2018). "Next, an siRNA knockdown approach was used to assess whether the CHI3L1/IL‐13Rα2 axis might be responsible for PCa tumor cell invasiveness driven by monocyte‐CM." (PMID 30094958, 2018). "Collectively, our observation suggests that siRNA complex methodology with dNP2-HA2 peptide could be a novel approach and an efficient way of siRNA delivery to T cells and intervene Chi3l1 expression for controlling tumor growth and progression." (PMID 29403003, 2018). "Activation of IL-13Rα2 by CHI3L1 triggered the activation of the mitogen-activated protein kinase signaling pathway, leading to the upregulated expression of matrix metalloproteinase genes, which promoted tumor metastasis." (PMID 28143526, 2017). "In accord with this finding, RLH activation with Poly(I:C) augmented granzyme B and perforin gene expression in lungs from tumor challenged mice and these effects were partially ameliorated when the levels of Chi3l1/YKL-40 were augmented using transgenic methodology." (PMID 27198666, 2016). "However, the mechanisms that Chi3l1 uses to mediate these responses and the pathways that control Chi3l1-induced tumor responses are poorly understood." (PMID 27198666, 2016).